ENSG00000212338
Synonyms: LOC124900432
Gene: Small nucleolar RNA gene on chromosome 1 (179,196,473 to 179,196,579, forward strand). Ensembl gene ENSG00000212338.
Gene Ontology:
Biological process: RNA processing
Cellular component: nucleolus
Homologues: Paralogues in human: SNORA67 (68% identical).